IL2 (interleukin 2)
Diseases named in the same sentence as IL2 in open-access papers (continued):
Sharing a sentence is not in itself a finding about the gene and the disease.
tumor (continued). "Indeed, mice carrying Treg-specific Ezh2 deficiency showed a reduced growth of different types of tumors (e.g., CRC, melanoma, prostate cancer) in association with the reprograming of tumor-infiltrating Tregs in anti-tumor effector cells (e.g., IL-2, IFNγ, and TNF)." (PMID 36900330, 2023). "Combination of local RT and intratumoral immunocytokine (IT-IC), consisting of anti-GD2 antibody linked to interleukin 2 (IL-2), achieved an in situ vaccine effect, where immunomodulating treatments of the tumor induce activation of local and then systemic T cell responses against tumor antigens." (PMID 37746303, 2023). "In addition, IL-2 overexpression could enhance antitumor response of directly treated tumors via release of tumor-associated antigen and consequent activation of T-cells." (PMID 35954434, 2022). "However, subsequent clinical applications found the short duration of IFN-α in patients, and IL-2 could cause emergent therapeutic toxicity, which led to their gradual withdrawal from tumor therapy." (PMID 33717106, 2021). "Also, there are efforts to isolate tumor reactive T cells with high expression of co-stimulatory molecules such 4-1BB or OX-40 or metabolically “fit” T cells as it is expected to reduce loss of anti-tumor function during expansion in IL-2 culture conditions." (PMID 34140957, 2021). "Hallmark analysis showed that the tumor-promoting pathways—DNA_REPAIR, G2M_CHECKPOINT, MTORC1_SIGNALING, and MYC_TARGETS_V1—were enriched in high-risk group, while the antitumor pathways—ALLOGRAFT_REJECTION and IL2_STAT5_SIGNALING—were mainly enriched in low-risk group." (PMID 34497605, 2021). "Another potential explanation could be that IL-2 primed NK cells are sensitized to apoptosis upon coming in contact with the vascular endothelium likely causing a reduction in migration of these cells to the tumor site and infiltration into the tumor." (PMID 30805309, 2019). "Finally, cytokines such as interleukin 2, which are particularly secreted from tumor cells, might damage interlobular bile ducts and cause portal fibrosis either directly or by an immunological mechanism." (PMID 31242930, 2019). "Elevated IL-2 levels could be derived from activated peripheral blood T-cells, as the described T-cell exhaustion with deficient IL-2 production seems to be restricted to tumor infiltrating T-cells." (PMID 30054667, 2018). "However, from the 1980s onwards, the prevailing notion began to turn once again as several multifunctional cytokines (e.g. interleukin-2, interferon-α) entered clinical testing, new data on tumour-associated antigens appeared, and adoptive T-cell transfer was used for the first time." (PMID 28571578, 2017). "Interestingly, a direct correlation existed between the extent of the tumor specificity obtained ex vivo and the clinical outcomes of the patients – higher tumor specificity and increased production of both IL-2 and IFNγ of the ex vivo product was associated with CRs." (PMID 27066005, 2016). "Past studies examining biomarkers associated with clinical benefit from high-dose IL-2 have yielded several potential strategies, including circulating vascular endothelial growth factor and fibronectin levels or T cell gene expression patterns on tumor biopsies." (PMID 26850630, 2016). "Hence, it is likely that anti-tumour responses in treated mice are linked to the accumulated CD11b+ DCs that could activate CD4 T cells to produce IL-2, necessary for the efficient generation of CD8 effector T cells." (PMID 27341421, 2016). "Although the natural course of response after IL-2 is not well defined, it may be important to allow sufficient time for immunotherapy to work before changing treatment approaches such as IL-2, as other forms of immunotherapy has been associated with delayed kinetics of tumor regression." (PMID 31546315, 2014). "Thus IL-2 can potentially be linked to NKG2D for its specific delivery to the tumor loci." (PMID 22509395, 2012).
tumor (continued). "Therefore, in the current study we determined if the anti-tumor effects in tumor-bearing mice receiving the CRT-E7 DNA vaccine could be enhanced by additional treatment with the DNA construct encoding NKG2D-Fc-IL2." (PMID 22509395, 2012). "Several studies including ours have also demonstrated that BCG could be engineered to express mucin-1 (MUC1), a candidade tumor-associated antigen for breast cancer and other epithelial adenocarcinomas, in a manner of multiple tandem repeats with coexpression of IL-2, GM-CSF, or CD80." (PMID 21941579, 2011). "Indeed, similar to NK cells cultured with undifferentiated sensitive tumor stem cells or primary untransformed stem cells, the treatment of NK cells with IL-2 and anti-CD16 mAb resulted in the loss of cytotoxicity, gain in IFN-γ secretion and down modulation of CD16 surface receptors." (PMID 20661281, 2010). "However, the mechanism underlying the biological effects of IL-2 on tumour growth is complex and it is still largely unknown." (PMID 19935800, 2009). "In a tumor model of MHC I-deficient mice, IL-2 transformed tumor-associated macrophages into M1 macrophages, which promoted cross-presentation of antigens to CD8+ T cells and thus restored immune cell infiltration." (PMID 41535643, 2026). "Combining IL-2 or GM-CSF with immune checkpoint inhibitors, like anti-PD-1 antibodies, can enhance the immune system's ability to overcome tumor-induced immunosuppression and promote sustained immune responses." (PMID 41355950, 2026). "Results revealed that tissue culture supplementation with IL-2 significantly reduced T regs within the TME via inhibiting the tumor expression of CD25 and Forkhead box P3 (FOXP3)." (PMID 42192107, 2026). "Studies using mouse models have shown that these IL-2-producing L. casei strains improve anti-cancer immune responses by strengthening the ability of T cells to target and kill tumor cells." (PMID 41355950, 2026). "In preclinical studies, IL-2-producing L. casei strains have been shown to enhance anti-tumor immunity and inhibit the growth of both primary and metastatic tumors in mouse models." (PMID 41355950, 2026). "The probiotic-based IL-2 delivery system promoted T-cell expansion and activation, while the checkpoint inhibitor blocked the inhibitory signals from the tumor, resulting in enhanced anti-tumor immunity." (PMID 41355950, 2026). "For instance, engineered E. coli strains expressing interleukin-2 (IL-2) or granulocyte-macrophage colony-stimulating factor (GM-CSF) have shown to stimulate robust immune responses and suppress tumor growth in mouse models." (PMID 41355950, 2026). "A study demonstrated that paeonol exerts antitumor effects intumor-bearing mice by inducing tumor cell apoptosis and stimulating interleukin-2 (IL-2) and TNF-αproduction." (PMID 41491143, 2026). "Liposomal formulations containing interleukin-2 (IL-2) or interferon-α have shown potential to activate T cells and enhancing tumor-specific immune responses." (PMID 41599391, 2026). "recently reported that Treg depletion prior to IL‐2 administration conferred superior antitumor efficacy in long‐term tumor outgrowth models relative to either monotherapy." (PMID 41550465, 2026). "The localized delivery of IL-2 by engineered probiotics can mitigate these issues by ensuring that IL-2 is released in proximity to the tumor, where its effects can be maximized while minimizing off-target effects." (PMID 41355950, 2026). "The traditional method of generating TILs starts with a high dose of interleukin (IL)-2 to induce the migration of TILs out of the tumor fragments and their proliferation in a 24-well plate." (PMID 40145091, 2025). "Collectively, these findings illustrate how the local immune context shapes the cellular responsiveness to IL-2-based therapies and help explain the context dependence of Treg dynamics in the tumor that was observed in our study." (PMID 40789741, 2025).
tumor (continued). "The help from CD4+ T cell–derived IL-2 in the tumor milieu is required for the full response of CD8+ cytotoxic T cells." (PMID 40759573, 2025). "Patients 117, 121, and 122 exhibited clear remodeling of their tumor microenvironments, with increased IL-2 and decreased IL-10 expression, mirroring our in vitro and murine results." (PMID 41459907, 2025). "T cell proliferation and differentiation within the TME and tumor-draining lymph nodes (TDLNs) are dependent on IL-2." (PMID 40508074, 2025). "Early clinical studies with elevated dosages of IL-2 demonstrated encouraging outcomes, with some patients showing tumor regression, representing a major step forward in immunotherapy." (PMID 40143046, 2025). "The systemic administration of HD IL-2 therapy (Aldesleukin) stimulates the activation of the immune cells, especially the effector T (Teff) cells and NK cells, which are anti-tumor cytotoxic cells." (PMID 41150778, 2025). "These conjugates selectively deliver IL-2 to the target sites of the tumor, allowing for the activation of the antitumor immune cells without causing activation of the normal tissues." (PMID 40309351, 2025). "This dynamic indicates that Tregs not only exert immunosuppressive functions autonomously but also compete for IL-2, inadvertently promoting tumor progression in PCa." (PMID 40698080, 2025). "We now consider a more realistic model of treatment which accounts for local transport of the IL-2-compound into the tumour via tissue boundaries (e.g. through blood vessels and capillaries on the boundary of the tissue region being modelled)." (PMID 40591070, 2025). "Interleukin-2 (IL-2) immunotherapy can induce durable tumor remissions, but its clinical performance has been limited by significant drawbacks such as short serum half-life and high toxicity." (PMID 40789741, 2025). "By inducing T cell expression of CD25, IL-2 enhances T cell signaling, thereby increasing the anti-tumor efficacy of cytotoxic T-lymphocytes (CTL) and chimeric antigen receptor T cells (CAR-T) used in immunotherapy." (PMID 39958351, 2025). "Analysis of the TME demonstrated increased gene expression of immune-related pathways, such as T cell receptor regulation of apoptosis and IL-2 signaling, in multiple spatially distinct tumor and stroma clusters." (PMID 41138165, 2025). "Recent research highlights the role of STAT5-related cytokines (IL-2 and IL-15) in tumor immunotherapy efficacy, with IL-15 cytokines inhibiting tumor growth and preventing metastasis, making them promising cancer treatment strategies." (PMID 39996811, 2025). "The results confirmed that APS inhibited tumour growth by modulating the immune function, as evidenced by the increased thymus and spleen indices and elevated levels of IL-2, IL-12, and TNF-α." (PMID 40649307, 2025). "Overall, these analyses highlight the tumor-specific effects of immunocytokine-targeted IL-2, promoting the growth of CD25+ NK cells while reducing the number of CD25+ Tregs." (PMID 40813233, 2025). "This blockade of the PD-1/PD-L1 axis restored CD8 + T cell function, as evidenced by increased proliferation and elevated secretion of IFN-γ and IL-2, contributing to tumor regression and TME remodeling." (PMID 41035884, 2025). "Immune cells themselves also have the ability to influence the tumor microenvironment by the cytokines they secrete, such as IL-2, which has been shown to improve the survival of T cells." (PMID 39941782, 2025). "In terms of tumour growth, triple therapy with prolonged IL-2 supplementation showed the most effective control of tumour growth within five weeks, outperforming the group with 3-day IL-2 injection." (PMID 40361460, 2025). "LAK therapy, once widely explored, has largely been abandoned due to poor tumor specificity and unacceptable toxicities related to high-dose IL-2 administration, such as vascular leak syndrome and systemic inflammation." (PMID 40904467, 2025).
tumor (continued). "When IL-2 is present, stimulation by phosphoantigens results in the selective and swift expansion of Vδ2 T cells ex vivo, which exhibit anti-tumor activity in vitro, as is observed in cases of multiple myeloma and renal cell carcinoma." (PMID 40148988, 2025). "Upon subsequent transfer to picomolar (pM) IL-2 concentrations, these cells undergo sustained vigorous proliferation and retain robust anti-tumor activity in long-term cultures." (PMID 41907300, 2025). "IL-2 can promote the proliferation and activation of T cells and NK cells, enhancing the anti-tumor activity of immune cells and promoting the apoptosis of glioma cells." (PMID 40183013, 2025). "The addition of an HPV vaccine had no impact on therapeutic outcome, similar to our preclinical observations that tumor-specific vaccination with adjuvants imiquimod and IL-2 was insufficient for tumor control." (PMID 39995843, 2025). "TILT-123 intended to mimic the effect of lymphodepleting chemotherapy and high-dose IL-2 by the viral expression of TNF and IL-2 locally in the tumor." (PMID 40107242, 2025). "Our results indicated that the TGF-βRII CAR T cells designed in this study exhibited robust activation and proliferation in response to TGF-β while maintaining moderate levels of IFN-γ and IL-2, both of which are crucial for anti-tumor immunity." (PMID 41403741, 2025). "Briefly, a metastatic lesion was surgically excised, and TIL were isolated by placing 24 tumor fragments into culture in presence of high concentration of IL-2." (PMID 41410746, 2025). "Th1 can secret anti-tumor cytokines, such as IFN-γ, TNF-α, and IL-2, which play an important role in anti-tumor immunity." (PMID 41237175, 2025). "Other than its signal transduction pathways, IL-2 has also been shown to effectively reduce tumor growth." (PMID 41584600, 2025). "Exosomes from activated NK cells (primary or NK92), stimulated with IL-2, IL-12, and IL-15, display increased penetrability, solid tumor targeting capacity, and enhanced cytotoxicity against tumor cells, attributed to granzyme B and H enrichment." (PMID 41511353, 2025). "This construct exhibited effective tumor inhibition with lower systemic toxicity compared to treatment with anti–PD-1 or IL-2 alone, or their combination." (PMID 41568361, 2025). "We found several key anti-tumor Th1 cytokines such as interleukin (IL)-2, IL-4, and interferon-γ, were stimulated by the combination therapy either systemically or in tumors or both, as well as anti-tumor biomarkers such as Granzyme B and perforin." (PMID 40104170, 2025). "The primary challenge to address is targeting IL-2 to the tumor to prolong its effect at this specific site; this to limit IL-2’s interaction with the α-chain of IL-2R on endothelial and pulmonary cells, which can lead to severe, life-threatening effects." (PMID 39852848, 2025). "OBP-301, an OAd with hTERT-driven E1A/E1B, showed strong anti-tumor activity in orthotopic and metastatic RCC mouse models, the anti-tumor effects were further enhanced by IL-2 co-administration." (PMID 41445946, 2025). "As a consequence of this immune activation, the tumor microenvironment becomes enriched with pro-inflammatory cytokines, such as interleukin-2 (IL-2), interleukin-6 (IL-6), interferon gamma (IFN-γ), and tumor necrosis factor alpha (TNF-α)." (PMID 40807154, 2025). "Research demonstrated that combining interleukin-2 (IL-2)-armed OVs with TIL therapy promoted tumor-specific TIL accumulation in hypoimmunogenic tumors, while reducing the proportion of exhausted PD-1hi Tim-3+ CD8+ cells and Tregs." (PMID 41024300, 2025). "DNMT inhibitors (DNMTis) like azacitidine and decitabine reactivate these genes and enhance tumor antigen presentation by boosting the expression of tumor-associated antigens (TAA) and cytokines such as IL-2 and IFN-γ." (PMID 40260236, 2025).
tumor (continued). "Another cytokine, interleukin-2 (IL-2), contributes to the activation of the immune system’s anti-tumor response, facilitating the elimination of malignant cells." (PMID 40869161, 2025). "T cells and monocytes secrete large amounts of pro-inflammatory cytokines, such as IL-2, IL-6, and TNFα, when co-cultured with TCam-2 cells, an effect which is significantly reduced when immune and tumor cells are separated by a Transwell insert." (PMID 40649953, 2025). "This is consistent with the role of T lymphocytes-particularly CD8+ T cells-in suppressing tumor growth via cytokine production, such as IL-2 and IL-15, and direct cytotoxic activity." (PMID 41367471, 2025). "TIL therapy, while autologous and relatively tumor-specific, is complicated by toxicities arising from lymphodepleting chemotherapy and high-dose IL-2." (PMID 40904467, 2025). "These are often adoptively transferred with concomitant adjuvants, such as lipopolysaccharide, in addition to IL-2 formulations to maximize the anti-tumor response." (PMID 40502703, 2025). "In an HPV-induced cancer model, administration of Lactibacillus casei BL23 led to increased IL-2 production, contributing to the suppression of tumor development." (PMID 41515150, 2025). "A complex coagulant consisting of fucoidan and polylysine was used to load IL-2, leading to the activation of tumor-reactive T cells at the tumor site through pH-adjusted injection gels." (PMID 41149588, 2025). "TIL therapy involves isolating, expanding, and reintroducing tumor-specific T cells into patients after lymphodepleting chemotherapy and IL2 administration to promote cell growth." (PMID 40075700, 2025). "Another interesting observation in our work was the variability in tumor Treg expansion depending on the IL-2 agonists that were employed." (PMID 40789741, 2025). "The process involves extracting tumor tissue, isolating TILs, expanding them with agents like interleukin-2 (IL-2), and reinfusing them to enhance the immune response against cancer." (PMID 40356763, 2025). "IL-2, a type of cytokine, stimulates T-lymphocytes and natural killer (NK) cells, enhancing their capacity to eliminate tumor cells." (PMID 40677703, 2025). "IL-2 stimulates the development and activation of CTLs and NK cells, which are essential for detecting and eliminating tumor cells." (PMID 40309351, 2025). "Within the tumor microenvironment (TME), the early stages are characterized by a predominance of M1 macrophages, NK cells, and CD4+/CD8 + T cells, which secrete anti-tumor factors including IL-2, IL-12, IL-18, and IFN-γ." (PMID 41384115, 2025). "Interleukin-2 (IL-2) is also added to the culture, which aids in the proliferation of tumor-specific T-cells." (PMID 40004731, 2025). "In studies on animal models (tumour mice), SPs induced immune responses, such as improving splenocyte proliferation by increasing IL-2, IFN-γ and CD8+ T cells." (PMID 40077614, 2025). "The AWT020 fusion protein offers a promising novel immunotherapeutic strategy by integrating PD-1 blockade and IL-2 signaling, conferring enhanced anti-tumor activity with reduced toxicity." (PMID 40046051, 2025). "By releasing cytokines such as IFN-γ, TNF, and IL-2, CD4+ T cells further promote the differentiation and activation of macrophages, CD8+ T cells, and NK cells, while limiting tumor-associated angiogenesis, thereby reinforcing antitumor responses." (PMID 41320679, 2025). "Multiple cytokines, including IL-2, IL-12, IL-10, and IL-4, showed significant reduction in tumor tissues derived from Gsdmd–/– mice compared with WT mice." (PMID 40759573, 2025). "In a cohort of 25 patients with solid tumors, treated with IL-2 and lymphokine-activated killer cells, 11 patients had objective tumor regression, and the tumors involved were melanoma, colorectal cancer, renal cell cancer and lung adenocarcinoma." (PMID 40305195, 2025).